GTSE1 (G2 and S-phase expressed 1)
Diseases named in the same sentence as GTSE1 in open-access papers (continued):
Sharing a sentence is not in itself a finding about the gene and the disease.
cancer (continued). "In fact, GTSE1 depletion rises the sensitivity of cancer cells to paclitaxel and cisplatin treatment." (PMID 28978043, 2017). "For these reasons, GTSE1 targeting will be further explored in the future as a way to interfere simultaneously with different aspects of cancer progression." (PMID 28978043, 2017). "In the last years, the number of evidence supporting a strong connection between GTSE1 misregulation and cancer progression has remarkably increased." (PMID 28978043, 2017). "We previously demonstrated that GTSE1 is able to promote focal adhesions disassembly and cancer cells migration, two main features of cells that have acquired metastatic capabilities." (PMID 28978043, 2017). "In particular, GTSE1 silencing increases the sensitivity of cancer cells to paclitaxel and cisplatin-induced cell death while in highly CIN cancer cell lines it diminishes the defects in chromosome segregation." (PMID 28978043, 2017). "This screening identified 61 unique analyses over all cancers where GTSE1 expression showed significantly higher expression in tumor tissues as compared to normal tissues." (PMID 23236459, 2012). "In this study, we proposed the immunoinfiltration relationship of GTSE1 in pan‐cancer for the first time, suggesting that enhanced expression of GTSE1 might significantly contribute to immune escape of tumor cells, thus affecting tumor progression." (PMID 38715380, 2024). "Similar to most cancers, GTSE1 exhibited significant clinical significance in LUAD." (PMID 38715380, 2024). "Due to limited research on GTSE1, we included literature from other cancer types." (PMID 39629227, 2024). "GTSE1 is a protein that is specifically expressed during the G2 and S phases of the cell cycle and is involved in the progression and metastasis of various cancers." (PMID 38464749, 2024). "Therefore, the correlation between HRD and GTSE1 expression across cancers was also investigated, and there was a positive correlation between HRD and GTSE1 in ccRCC (p < 0.001)." (PMID 36999057, 2023). "Genes containing AS events associated with overall survival are known components of cancer-related pathways, including regulation of transcription (E2F4, ZNF730, GPBP1, POLR2J, SP2, and CIART), cell cycle (E2F4 and GTSE1), or cell-cell adhesion (CEACAM1, MMP14, EPS8L2, AP3D1, AFDN, and PAK4)." (PMID 35044822, 2022). "Gtse1 has been found to be overexpressed in a variety of cancers." (PMID 35783385, 2022). "The expression of G2 and S phase-expressed-1 (GTSE1) was upregulated in human cancer." (PMID 34007784, 2021). "GTSE1 could promote the growth of cancer cell via activating the AKT pathway and promote tumor metastasis by EMT pathway." (PMID 34818353, 2021). "In sum, Bel-7404 cells with GTSE1 knockdown exhibited fewer characteristics of cancer cells." (PMID 32082966, 2019). "Moreover, we showed that TEAD regulates the formation of cell protrusions necessary for cancer cells migration through GTSE1 providing, for the first time, a mechanistic explanation of how it affects cell migration." (PMID 28978043, 2017). "Further study indicated that overexpression of GTSE1 was frequently detected in human cancers." (PMID 27240802, 2016). "Using data from TCGA, ArrayExpress, and GEO databases, GTSE1 was found to be significantly overexpressed in various tumors, correlating with clinical features and survival rates, suggesting its potential as a biomarker for pan‐cancer prognosis and a target for immunotherapy." (PMID 38715380, 2024). "GTSE1 might be a potential biomarker for the prognosis of pan‐cancer." (PMID 38715380, 2024).
cancer (continued). "Likewise, TPX2 has been studied as a factor critical for mitosis and spindle assembly and as a marker for diagnosis and prognosis when overexpressed in cancer; GTSE1 can also act as an oncogene and a high expression was positively correlated with histological grade and poor survival." (PMID 35954157, 2022). "GTSE1 has been reported as significantly overexpressed in different tumors, suggesting that cell cycle misregulation and/or overexpression of an important GTSE1 activity may play a role in cancer progression." (PMID 23236459, 2012). "Trajectory and pseudotime analysis showed that GTSE1+ OB cells were the origin of cancer cells, and CTSD+ OB cells were the end of cancer cells during the developmental trajectory." (PMID 40831537, 2025). "In bulk datasets, GTSE1+ OB cells and CREB3L1+ CB cells were marked by high infiltration in metastatic samples, suggesting that GTSE1+ OB cells and CREB3L1+ CB cells are two metastasis-enrich cancer cells." (PMID 40831537, 2025). "G2 and S-phase expressed 1 (GTSE1) is a regulatory protein found in the cytoplasm of the cell, which plays a key role in the cell cycle distribution of a wide range of cancer cells and is involved in life processes such as cell proliferation and apoptosis." (PMID 39026496, 2024). "The findings indicated upregulation of GTSE1 in LUAD tissues, showing good discriminatory potential for this type of cancer." (PMID 38715380, 2024). "The data suggested that GTSE1 expression was significantly correlated with KIRC subtype, cancer stage, nodal metastasis, and tumor grade." (PMID 36999057, 2023). "Risk signature contigs mapped at least five other genes with established driver roles in PCa or other cancers: CAMK2N1, COL1A1, GTSE1 and PTPRN2, supporting the relevance of these sequence contigs in PCa etiology." (PMID 33845808, 2021). "Meta-analysis using a random effects model showed a pooled standardized mean difference (SMD) value of 1.22, indicating a higher expression of GTSE1 mRNA in cancer tissues compared to normal tissues and adjacent non-cancerous tissues." (PMID 39629227, 2024). "In this study, results demonstrated that GTSE1 expression effectively distinguished cancer tissues from normal tissues in the 21 tumor types included in this study (sensitivity = 0.89, specificity = 0.92, area under the curve = 0.96)." (PMID 38715380, 2024). "Although more and more evidences support the significant involvement of GTSE1 in the development of different carcinoma types, most studies had focused on individual cancers, lacking a systematic pan‐cancer analysis of GTSE1." (PMID 38715380, 2024). "In addition to GTSE1, overexpression of CDC20, PCNA, and MCM has been detected in many types of human cancer." (PMID 32082966, 2019). "In human cancer cells, the absence of GTSE1 has been shown to inhibit cell proliferation." (PMID 39940790, 2025). "Furthermore, ligand–receptor analysis showed preferential interactions of C5AR1-RPS19 and CD74-MIF pairs between GTSE1+ OB cells and CREB3L1+ CB cells in metastasis, which could promote cancer cell growth and metastasis." (PMID 40831537, 2025). "In our study, DEGs in GTSE1 knockdown HCC cells were enriched in critical steps of oncogenesis including dysregulated cell cycle and unlimited cell growth, which might account for the adverse cancer prognosis." (PMID 32082966, 2019). "The GTSE1 level was approximately 100-fold higher in cancer tissues than in non-cancerous tissues." (PMID 28698581, 2017). "In conclusion, our finding reveals that GTSE1+ OB cells and CREB3L1+ CB cells enrich in metastatic OS, and a coordinated pro-metastatic tumor microenvironment driven by cancer cells and non-malignant cells." (PMID 40831537, 2025).
cancer (continued). "The majority (27/28, 96.4%) of cancers, including HCC, showed increased levels of GTSE1 in tumour tissues compared with non-tumour tissues." (PMID 28698581, 2017).
tumor (32 papers, 2012 to 2025). "GTSE1 has been implicated in the control of tumor initiation and progression in various malignancies, including breast cancer, prostate cancer, and colon cancer." (PMID 39629227, 2024). "Current studies have confirmed that GTSE1 expression is upregulated in a variety of tumors and is also associated with worse prognosis in tumor patients." (PMID 36999057, 2023). "Statistical analysis using the Kaplan-Meier method revealed a striking association between GTSE1 expression and tumour-specific 10-year overall survival (OS)." (PMID 28698581, 2017). "We sought to assess the effect of GTSE1 loss in OB cells on tumor growth and metastasis in vitro." (PMID 40831537, 2025). "Furthermore, overexpression of GTSE1 was associated with unfavorable prognosis in various tumor types." (PMID 38715380, 2024). "Therefore, it was crucial to explore the association of GTSE1 expression levels, prognosis of patients, and tumor immune infiltration levels across various tumor types, including LUAD." (PMID 38715380, 2024). "Immune infiltration exerts a significant impact on tumor development, although it is not yet fully understood whether GTSE1 is associated with tumor immune invasion." (PMID 38715380, 2024). "Additionally, high GTSE1 expression contributes to an increased level of immune cell infiltration and is associated with a worse prognosis, providing a potential target for tumor therapy in ccRCC." (PMID 36999057, 2023). "Furthermore, high GTSE1 expression was positively associated with tumor size, venous invasion, advanced tumor stage, and short overall survival." (PMID 27240802, 2016). "Furthermore, loss of function assays on GTSE1 indicated that inhibition of GTSE1 was not only significantly decreased HCC tumor growth in vitro and in vivo but also suppressed the migration and invasion in vitro." (PMID 27240802, 2016). "Specifically, for the G2 and S phase-expressed-1 (GTSE1) protein, its expression is known to be significantly upregulated in BC tissues and cell lines, with high levels of this protein correlating with tumor prevalence and poor prognosis." (PMID 40310419, 2025). "It has been shown that GTSE1 promotes tumor cell proliferation by activating the AKT signaling pathway and enhances metastasis through the regulation of the epithelial–mesenchymal transition." (PMID 40310419, 2025). "This study, comprising 9358 tumor samples and 722 control samples, undertook a comprehensive investigation into the differential expression of GTSE1 between cancerous and control tissues across diverse human tumor types." (PMID 38715380, 2024). "Subsequently, we conducted a detailed investigation into the correlation between GTSE1 expression and the tumor immune microenvironment." (PMID 39629227, 2024). "GTSE1 exhibited significantly increased expression levels in a wide range of tumor tissues in contrast with normal tissues (p < 0.05)." (PMID 38715380, 2024). "To clarify the relationship of elevated expression levels of GTSE1 with overall survival across different tumor types, we conducted an analysis on the clinical features and overall survival of the included samples." (PMID 38715380, 2024). "When compared to the mice with sh-NC, the tumor weight and volume were much lower in the GTSE1 knockdown mice." (PMID 38698443, 2024). "In brief, these results revealed that GTSE1 was positively correlated with immune cell infiltration and tumor microenvironment characteristics, especially macrophages." (PMID 36999057, 2023).
tumor (continued). "In this research, we first investigated the expression profiles of GTSE1 in ccRCC and identified its biological functions, potential clinical value, and relationship with tumor-infiltrating immune cells (TIICs) in ccRCC." (PMID 36999057, 2023). "In terms of the tumor microenvironment, GTSE1 was positively correlated with the StromalScore, ImmuneScore, and EstimateScore but negatively correlated with tumor purity." (PMID 36999057, 2023). "In the clinical tissue samples, GTSE1 expression was elevated in OS tumor tissues relative to the adjacent tissues according to RT-qPCR and IHC staining assays." (PMID 34876170, 2021). "Downregulation of GTSE1 further promoted, whereas overexpression of GTSE1 reduced cell apoptosis in the xenograft tumor tissues." (PMID 34876170, 2021). "Silencing of GTSE1 strengthened, whereas overexpression of GTSE1 blocked the tumor-eliminating function of CDDP in nude mice." (PMID 34876170, 2021). "GTSE1 inhibition significantly decreased tumor growth in vitro and in vivo, and suppressed migration and invasion in vitro." (PMID 30406363, 2019). "To address the cellular mechanisms of GTSE1 responsible for tumour progression, we established stable hepatocellular cell lines (QGY-7703, SMMC-7721) in which GTSE1 was suppressed via a shRNA expressing vector or overexpressed using a GTSE1 expressing vector." (PMID 28698581, 2017). "We found that in Anti-45A tumour nodules GTSE1 expression is significantly reduced with respect to Mock tumor nodules." (PMID 28029658, 2017). "We used human HCC samples and cell lines to address the cellular and molecular mechanisms by which GTSE1 promotes hepatic malignant transformation and tumour progression." (PMID 28698581, 2017). "Univariate analysis showed that GTSE1, tumor size, vascular invasion, and tumor-node-metastasis stage were significantly associated with OS in HCC patients." (PMID 27240802, 2016). "Consistent with results in vitro, tumor growth in GTSE1 silencing group was obviously slower than that in the SCR group." (PMID 27240802, 2016). "In the current study, we show that GTSE1 was overexpressed and correlated with tumor invasion and worse outcome in HCC." (PMID 27240802, 2016). "In our present study, we first found that GTSE1 was frequently upregulated in HCC tissues and cells and the increased GTSE1 expression was closely related to tumor size, venous invasion, and advanced stage of HCC." (PMID 27240802, 2016). "Together these data show a correlative relationship between the misregulation and overexpression of GTSE1 found in tumors, and tumor invasiveness and prognosis." (PMID 23236459, 2012). "Furthermore, the correlation between GTSE1 expression and the tumor microenvironment, immune cell infiltration, and immune checkpoints was assessed using ESTIMATE and CIBERSORT algorithms." (PMID 39629227, 2024). "Secondly, the relationship between GTSE1 expression and the tumor immune microenvironment, as well as the signaling pathways involving GTSE1 in regulating LUAD development, remains unclear, necessitating further investigation." (PMID 39629227, 2024). "Furthermore, the correlation between GTSE1 expression and levels of immune infiltration was assessed by utilizing the Tumor Immune Estimate Resource (TIMER) database to calculate the Spearman rank correlation coefficient." (PMID 38715380, 2024). "Taken together, GTSE1 could promote tumor progression and serve as a potential biomarker and prognostic predictor in ccRCC." (PMID 36999057, 2023). "Moreover, we further explored the correlation between GTSE1 and immune infiltration in four aspects (tumor microenvironment, immune cell infiltration, immune cell markers, and immune checkpoints)." (PMID 36999057, 2023). "Upregulated GTSE1 correlates with tumor stage, invasive potential, and distant metastasis." (PMID 34007784, 2021).
tumor (continued). "Moreover, the function of GTSE1 was further validated in vivo, where knockdown of GTSE1 reduced the volume and weight of xenograft tumors following CDDP treatment, whereas overexpression of GTSE1 blocked the tumor-eliminating role of CDDP." (PMID 34876170, 2021). "GTSE1 has also been reported to play a tumor-promoting role through triggering cell proliferation." (PMID 34876170, 2021). "The increase in GTSE1 expression was associated with poor HCC prognosis, suggesting that this gene product may function as an oncogene and may play a pivotal role in tumour progression and metastasis." (PMID 28698581, 2017). "A Chi-square analysis showed that patients with higher GTSE1 expression were more likely to have multiple tumours and to have higher alpha-fetoprotein (AFP) levels, whereas patients with lower GTSE1 expression were prone to having a single tumour and lower AFP levels." (PMID 28698581, 2017). "Taken together, these results demonstrated that GTSE1 expression was increased in HCC tumour tissues and implied that the upregulation of GTSE1 in HCC might play a considerable role in tumour development." (PMID 28698581, 2017). "In the light of the increased compactness of Anti-45A tumor nodules, we hypothesized a correlation between the level of GTSE1 protein and the invasiveness/migration capability dependent on microtubule organization." (PMID 28029658, 2017). "To verify this hypothesis, we analyzed GTSE1 protein level in tumor nodules from Mock and Anti-45A mice in immunohistochemistry experiments." (PMID 28029658, 2017). "Notably, we demonstrated that 45A ncRNA downregulation in malignant NB cells strongly affects tumor progression, increasing tumor nodule compactness and reducing GTSE1 protein expression (Q9NYZ3) in a mouse subcutaneous NB model." (PMID 28029658, 2017). "Furthermore, knockdown of GTSE1 repressed the tumor volume and tumor weight of xenografted mice." (PMID 38698443, 2024). "In addition, the in vivo role of GTSE1 was addressed in tumor-bearing mice." (PMID 38698443, 2024). "Furthermore, the tumor volume and weight of xenografted mice were reduced by GTSE1 knockdown." (PMID 38698443, 2024). "Thus, this study investigated the relationship of GTSE1 and tumor immune infiltration." (PMID 38715380, 2024). "However, overexpression of GTSE1 blocked the anti-tumor effect of CDDP." (PMID 34876170, 2021). "Thus, GTSE1 is considered as a stimulator of tumour migration and invasion." (PMID 28698581, 2017). "GTSE1+ OB cells, monocytes, CD8+ T cells, CREB3L1+ CB cells, and fibroblasts jointly coordinated the formation of pro-metastatic tumor microenvironment." (PMID 40831537, 2025). "According to an analysis using tumor tissues from NPC patients, the expression of GTSE1 was considerably upregulated in NPC samples when compared to control samples." (PMID 38698443, 2024). "Knock-down results showed that downregulation of GTSE1 suppressed proliferation, mobility, invasion and angiogenesis of NPC cells, and also inhibited the tumor growth in the NPC xenografted mice." (PMID 38698443, 2024). "GSEA also found that GTSE1 extremely participated in the epithelial-mesenchymal transition (EMT), which provided the driving force for tumor metastasis." (PMID 36999057, 2023). "GTSE1 works by regulating the expression of Krüppel-like factor 4 (KLF4), which is a tumor suppressor." (PMID 37370817, 2023). "Cell cycle-related genes such as AURKA, AURKB, GTSE1, CCNA2, and MYBL2 were shown to promote tumor progression of LUAD." (PMID 36304306, 2022). "Others have proposed that overexpression of the RRM2, GTSE1 and EXO1 genes in HNSCC have active roles in tumor progression and inhibition of the apoptosis pathway." (PMID 34231338, 2021).